FOXM1 (forkhead box M1)
Diseases named in the same sentence as FOXM1 in open-access papers (continued):
Sharing a sentence is not in itself a finding about the gene and the disease.
prostate carcinoma (continued). "Thus, our study revealed that miR-877-5p may also drive cell proliferation, migration, and invasion of prostate cancer cells by targeting FOXM1." (PMID 34654353, 2021). "Thus, targeting FOXM1 expression by inhibiting SETD1A may serve as a fundamental alternative to treating prostate cancer." (PMID 32629770, 2020). "Thus, the knockout of ATG7, Beclin-1, or treatment with CQ restored the antitumor effect of docetaxel, demonstrating that either autophagy or FOXM1 may be potential targets for combined therapies with docetaxel to treat metastatic prostate cancer patients." (PMID 33335860, 2020). "Thus, the regulation of FOXM1 expression by SETD1A suggests that SETD1A may play a key role in prostate cancer growth, metastasis, and castration resistance." (PMID 32629770, 2020). "In conclusion, FoxM1 was significantly increased in prostate cancer samples, and it could regulate the proliferative and invasive ability of prostate cancer cells which might be a new target for prostate cancer." (PMID 29554906, 2018). "Besides, we found a new regulatory mechanism of FoxM1 in prostate cancer that was c-Myc could regulate the expression of FoxM1 by directly binding to its promoter." (PMID 29554906, 2018). "Moreover, overexpression of FoxM1 coincides with metastasis of prostate cancer." (PMID 23006512, 2012). "A functional interaction between CENP‐F and the PI3K/AKT signaling pathway has been observed in DU145 prostate cancer cells, where the PI3K/AKT signaling pathway is completely eliminated when CENP‐F and FOXM1 are co‐silenced." (PMID 40387105, 2025). "In a prostate cancer study, monensin was found to bind to the DNA-binding domain (DBD) of FOXM1, reducing its interaction with downstream target genes such as PLK1 and CDC25B, thereby exerting an anti-cancer effect." (PMID 40612352, 2025). "Furthermore, OGT knockdown in prostate cancer cell lines was associated with reduced expression of MMP-2, MMP-9, and vascular endothelial growth factor (VEGF), thereby inhibiting invasion and angiogenesis through the regulation of the oncogenic transcription factor forkhead box M1 (FoxM1)." (PMID 39285476, 2024). "FOXM1 and CDK1 from the KEGG Senescence pathway and EGFR from the Prostate Cancer Pathway are also involved in the DNA repair process." (PMID 35205253, 2022). "Castration-resistant prostate cancer cell-secreted exosomes were found to be directly internalized into prostate cancer (PCa) cells, transferring HOXD-AS1 and modulating the miR-361-5p/FOXM1 axis." (PMID 36338993, 2022). "The spatial transcriptome sequencing results acquired from SpatialDB showed the location of FOXM1 and NEIL3 expressions in prostate cancer." (PMID 35392496, 2022). "In prostate cancer, NIC suppresses the proliferation of prostate cancer cells by inhibiting the FOXM1-mediated DNA damage response." (PMID 36555754, 2022). "Other studies showed that forkhead box M1 (FOXM1) and CENPF synergistically promoted malignant progression and poor prognosis of prostate cancer." (PMID 33428600, 2021). "In test sets containing data of LNCaP and C4-2B (GSE107782), and other types of prostate cancer cell lines (GSE50936), we found that FOXM1 mRNA expression was significantly and positively correlated with that of SETD1A." (PMID 32629770, 2020). "A similar result was exhibited in docetaxel resistant prostate cancer cell lines (PC3-DR and VCaP-DR): these cells present enhanced autophagy activity through the overexpression of Forkhead box protein M1 (FOXM1)." (PMID 33335860, 2020). "Knockdown of miR‐193b targets FOXM1 and RRM2 in prostate cancer cells phenocopied overexpression of miR‐193b." (PMID 31225930, 2019). "FOXM1 and UHRF1 are also consistently expressed in prostate cancer tumor specimens and cells, with high correlation between the two molecules." (PMID 29752436, 2018).
prostate carcinoma (continued). "miR-31 has a known role in prostate cancer and melanoma, suppressing key cell cycle regulators and pro-oncogenic genes such as CDK1, E2F2, EXO1, FOXM1, MCM2, Src or MET." (PMID 25644061, 2015). "AKT can control FOXM1 expression in osteosarcoma, and the downregulation of AKT by siRNA has been shown to inhibit FOXM1 expression; whereas the overexpression of AKT increased FOXM1 expression in prostate cancer." (PMID 26640950, 2015). "The present study identified novel molecular mechanism of prostate cancer progression, providing a crosstalk between SPDEF tumor suppressor and Foxm1 oncogene." (PMID 25254494, 2014). "In prostate cancer patients, the low SPDEF and high Foxm1 were found in most aggressive prostate tumors that were associated with poor prognosis." (PMID 25254494, 2014). "Anti-FOXM1 antibody was used to immunoprecipitate regions of chromatin bound by FOXM1 in U2OS osteosarcoma cells and CWR22rv prostate cancer cells." (PMID 23240008, 2012). "Specifically for prostate cancer, when survival was tested using different datasets and more data, the negative prognostic power of FOXM1 in cancer survival became apparent." (PMID 39858603, 2025). "In cancer, FOXM1 is generally considered a marker for poor prognosis in cancer survival studies, often as a co-effector with other cancer master regulators, such as CENPF in prostate cancer and MYB in lymphoma." (PMID 39858603, 2025). "Identification of FOXM1 and CENPF as synergistic master regulators in aggressive prostate cancer showed that co-targeting these factors could revert malignant phenotypes despite underlying genetic alterations." (PMID 41614813, 2025). "Therefore, we sought to investigate the anticancer effects of the novel FOXM1 inhibitor, STL001 in a variety of human cancers from solid tumors including ovarian, colorectal, breast, esophageal, and prostate cancers." (PMID 38697979, 2024). "In prostate cancer, NIC induces apoptosis by inhibiting the FOXM1-mediated DNA damage response." (PMID 36555754, 2022). "Besides, the dysregulation of FOXM1-CENPF due to miRNAs was discovered to contribute to the metastasis and drug resistance of prostate cancer." (PMID 35392496, 2022). "Besides, the expression of FOXM1 was promoted by SETD1A, which was expressed higher in CPRC than primary prostate cancer and facilitated stem cell factors and stem cell formation in metastatic CRPC." (PMID 35392496, 2022). "Besides, previous research has demonstrated that several transcription factors, such as FOXM1, MYC, APC/C/CDH1, and E2F, targeted RRM2 in prostate cancer." (PMID 36202136, 2022). "Accordingly, we did not observe uniform FOXM1 upregulation in prostate cancer cells treated with docetaxel or NSCLC cells treated with paclitaxel." (PMID 34262016, 2021). "whereas, there is no research on the mechanism of miR-877-5p in prostate cancer, let alone combined with FOXM1." (PMID 34654353, 2021). "FOXM1 expression was upregulated in the docetaxel resistant prostate cancer cell lines, downregulation of ATG7, Beclin 1, or cotreatment with chloroquine partly restored sensitivity to docetaxel in the FOXM1-overexpressing prostate cancer cells." (PMID 32587255, 2020). "FOXM1 and CENPF co-expression could be a potential robust prognostic indicator of poor survival and metastasis in prostate cancer, and these two genes may contribute to driving prostate cancer." (PMID 32040444, 2020). "Presently, we demonstrated the mechanism by which SETD1A regulates the FOXM1 pathway and showed that it does not affect the AR pathway in prostate cancer cells." (PMID 32629770, 2020). "In addition, FOXM1 and UHRF1 are highly correlated in tumor specimens and prostate cancer cell lines." (PMID 29752436, 2018). "FOXM1 or UHRF1 expression levels showed high correlation in prostate cancer cells and non-malignant prostate epithelial cells." (PMID 29752436, 2018).
prostate carcinoma (continued). "In addition, the expression of IL1R1, FOXM1 and PC4 changes markedly during the progression of normal prostate to metastasised prostate cancer." (PMID 15642172, 2005). "Honokiol is a small molecule inhibitor that binds to the transactivation domain of FOXM1 and inhibits FOXM transcriptional activity by preventing its binding to DNA, leading to the suppression of cell proliferation of breast, lung, pancreatic, and prostate cancers." (PMID 39594778, 2024). "In prostate cancer and TNBC, honokiol inhibits FOXM1 but does not cause proteasomal degradation." (PMID 39594778, 2024). "Furthermore, SR9009 could inhibit prostate cancer subtype 1 (PCS1), the most lethal and aggressive PCa, by mediating the LXRα/FOXM1 pathway independently of REV-ERBs." (PMID 36357378, 2022). "However, the expression level of FoxM1 in prostate cancer and its clinical significance in the progression of prostate cancer have not been fully studied." (PMID 29554906, 2018). "However, the potential mechanism of elevated FoxM1 and c-Myc to the development of prostate cancer has not been identified." (PMID 29554906, 2018). "FOXM1 is higher in prostate cancer cells than the non-malignant prostate epithelial cells." (PMID 28199985, 2017). "Likewise, mouse hepatocytes that are deficient in FOXM1 failed to proliferate and are highly resistant to developing carcinogen-induced liver tumors, while FOXM1-overexpression in LADY and TRAMP prostate cancer models resulted in accelerated development, proliferation, and growth of prostate tumors." (PMID 37370117, 2023). "SR9009 treatment markedly inhibited prostate cancer subtype 1 (PCS1), the most lethal and aggressive PCa subtype, through FOXM1 pathway blockade, while it had no impacts on PCS2 and PCS3." (PMID 36357378, 2022). "In the genes of the MEmagenta module, we found that the known genes closely related to cancer stemness in non-prostate cancer, such as BRCA1, EZH2, FOXM1, CDC20, and CDCA8, were all clustered in this module, indicating these genes were also closely related to the stemness of prostate cancer cells." (PMID 33985534, 2021). "Additionally, we assessed the expression of FOXM1 and UHRF1 proteins in a panel of prostate cancer cell lines and non-malignant prostate epithelial cells." (PMID 29752436, 2018). "AKT can control FOXM1 expression in osteosarcoma, and the downregulation of AKT by siRNA has been shown to inhibit FOXM1 expression, whereas the overexpression of AKT has been shown to increase FOXM1 expression in prostate cancer; however, its role in melanoma cells has not been reported." (PMID 26640950, 2015).
colorectal cancer (88 papers, 2012 to 2025). A primary or metastatic malignant neoplasm that affects the colon or rectum. "The colorectal cancer meta-analysis associates high FOXM1 expression with a poor 5-year survival of patients." (PMID 38697979, 2024). "MiR-761 expression was negatively associated with the expression of FOXM1 in colorectal cancer tissues." (PMID 29416616, 2018). "FOXM1 is overexpressed in many human cancers and is associated with a poor prognosis, such as breast, oral cavity squamous cell carcinoma, head and neck, bladder, esophageal and colorectal cancers." (PMID 35313071, 2022). "In addition, miR-761 expression was negatively associated with the expression of FOXM1 in colorectal cancer tissues." (PMID 29416616, 2018). "Furthermore, the miR-761 expression was negatively associated with the expression of FOXM1 in colorectal cancer tissues." (PMID 29416616, 2018). "FOXM1 modulates expression levels of thymidylate synthase, contributing to resistance of 5-FU in colorectal cancer as well." (PMID 40777019, 2025). "For instance, miR-215-3p can suppress colorectal cancer growth and aggression by inhibiting Forkhead box protein M1 (FOXM1) expression." (PMID 39736850, 2025). "Previous studies have found that the co-expression of FOXM1 and TOP2A is significantly associated with poor prognosis in patients with colorectal cancer, bladder cancer, etc." (PMID 40589640, 2025). "iRegulon analysis identified the oncogenic transcription factor FOXM1 as a key regulatory molecule in colorectal cancer growth." (PMID 38425293, 2024). "The ectopic overexpression of miR-532-3p in colorectal cancer (CRC) cells led to decreased FOXM1 levels which resulted in the alteration of CRC functionalities." (PMID 39272919, 2024). "Correspondingly, upregulation of the FOXM1 protein was observed in colorectal cancer SW480 and HCT‐116 cells compared with normal CCD841 cells." (PMID 38425293, 2024). "Similar to esophageal cancer, STL001 in combination with 5-FU therapy remarkably decreased 5-FU-induced FOXM1 levels and significantly enhanced the sensitivity of colorectal cancer cells (HCT-116 and FET) to the cytotoxic effects of 5-FU therapy." (PMID 38697979, 2024). "Treatment of colorectal cancer cells with PF leads to downregulation of FoxM1 and inhibits colorectal cancer cell migration." (PMID 36339551, 2022). "Our previous studies and other groups have also highlighted the role of FOXM1 activation in colorectal cancer and TNBC." (PMID 34565361, 2021). "Our previous study in colorectal cancer reported FOXM1 to be a novel target for epigenetic regulation by the miR-320 family." (PMID 34565361, 2021). "Increasing the expression of FOXM1 on the carcinogenic effects of colorectal cancer through β-catenin activation signaling pathway." (PMID 34252882, 2021). "In another example, circCTNNA1 promotes colorectal cancer progression via circCTNNA1/miR-149-5p/FOXM1 axis." (PMID 34055775, 2021). "We found that the expression of Rab1A and FoxM1 was significantly higher in colorectal cancer tissues than in normal tissues (P < 0.001, P < 0.001)." (PMID 33214609, 2020). "A recent study reported that GLI1 expression is closely associated with FoxM1 expression and that GLI1 expression elevation promotes colorectal cancer metastasis via FoxM1 overexpression." (PMID 33214609, 2020). "A previous study shows that aberrant overexpression of GLI1 promotes colorectal cancer metastasis via FoxM1 overexpression." (PMID 33214609, 2020). "First, immunohistochemistry (IHC) staining was performed in 135 pairs of colorectal cancer and adjacent normal tissues to detect Rab1A and FoxM1 expression." (PMID 33214609, 2020). "Colorectal cancer cell proliferation was also enhanced in the background of Hh signaling and FOXM1 expression." (PMID 33680951, 2020). "AXL dimerizes with epidermal growth factor receptor (EGFR), which has been shown to regulate FOXM1 expression via an EGFR/RAS/FOXM1/β-catenin axis in colorectal cancer." (PMID 32976773, 2020).
colorectal cancer (continued). "(A) Cluster analysis of 135 pairs of colorectal cancer (green) and normal tissues (red) based on Rab1A and FoxM1 IHC scores." (PMID 33214609, 2020). "To investigate the functional correlations between the two proteins, we investigated the role of FOXM1 in 5-FU resistance in colorectal cancer cell lines." (PMID 30728402, 2019). "In colorectal cancer, FOXM1 has been shown to be involved in carcinogenesis using a Rosa26-FOXM1 transgenic mouse model." (PMID 30728402, 2019). "In human colorectal cancer tissue specimens, a strong correlation of FOXM1 and TYMS staining was observed." (PMID 30728402, 2019). "FoxM1 was identified as a down-stream target by mRNA microarray, implying that FoxM1 plays a main role in determining how E2A regulates the tumor-initiating capacity of colorectal cancer." (PMID 31234887, 2019). "Xu showed that miR-149 can directly inhibit FOXM1, thereby inhibiting the invasion and migration of colorectal cancer cells." (PMID 30250169, 2018). "In this study, we also found that the expression of FOXM1 was upregulated in colorectal cancer cell lines and tissues." (PMID 29416616, 2018). "Ectopic expression of miR-761 inhibited colorectal cancer cell proliferation and invasion by downregulating FOXM1 expression." (PMID 29416616, 2018). "Transcription factor forkhead box M1 (FOXM1) is a crucial regulator in colorectal cancer (CRC) progression." (PMID 30486864, 2018). "The study aims to assess the relationship between FoxM1 expression and clinicopathological parameters and prognosis of patients diagnosed with colorectal cancer (CRC) by summarizing the studies included." (PMID 30593202, 2018). "Overexpression of miR-761 promoted the sensitivity of colorectal cancer cells to 5-FU and ectopic expression of miR-761 suppressed colorectal cancer cell proliferation, cell cycle, colony formation and invasion partly through regulating FOXM1 expression." (PMID 29416616, 2018). "The results so far obtained indicate that the anti-proliferative response to treatment with cetuximab and/or celecoxib is related to FOXM1 and b-catenin expression and their nuclear localization in colorectal cancer cells." (PMID 28423516, 2017). "So, we concluded that Gli1 also promoted colorectal cancer cells migration and invasion in a Foxm1-dependent manner in vivo." (PMID 27863385, 2016). "In this study, consistent with previous reports, we also found that FOXM1 mRNA and protein levels were higher in colorectal cancer than in adjacent normal tissue." (PMID 27034162, 2016). "To exclude the possibility of transcriptional upregulation of both HSPA5 and FOXM1 induced by hypoxia in advanced colorectal cancer, we analyzed the correlation between FOXM1 and spliced XBP1 mRNA, an indicator of ER stress." (PMID 27034162, 2016). "Several studies have shown that increased expression of FOXM1 induced colorectal cancer cell migration and invasion." (PMID 27034162, 2016). "In this study, a significant positive correlation of FOXM1 with HSPA5 mRNA expression was observed in colorectal cancer specimens." (PMID 27034162, 2016). "Previous reports show FOXM1 promotes tumorigenesis and is widely overexpressed in a multitude of human solid tumors, including colorectal cancer." (PMID 27034162, 2016). "Lastly, our results suggested FOXM1 facilitated the activities and expressions of MMP2 and 9 associated with cell-surface HSPA5 in colorectal cancer cells." (PMID 27034162, 2016). "To investigate the relationship between FOXM1 with ER stress in colorectal cancer, we first analyzed HSPA5, spliced XBP1 and FOXM1 mRNA expression by qRT-PCR in colorectal cancer specimens." (PMID 27034162, 2016).